CRP (C-reactive protein)
Diseases named in the same sentence as CRP in open-access papers (continued):
Sharing a sentence is not in itself a finding about the gene and the disease.
Sepsis (continued). "Six of eight patients with a second rise in CRP (75.0%) had postoperative infectious complications (pneumonia, four; CRBSI, one; sepsis of unknown cause, one)." (PMID 25888882, 2015). "Elevated CRP circulatory levels were found in inflammatory conditions such as Crohn’s disease, inflammatory bowel disease, ulcerative colitis, infections, necrosis, malignancy, sepsis, and severe trauma." (PMID 26312071, 2015). "Procalcitonin (PCT) and C-reactive protein (CRP) are the most frequently used biomarkers in sepsis." (PMID 26367532, 2015). "Among these markers, CRP is readily accessible in the critical care setting, and its value as a prognostic marker is proven in many diseases, including cerebral disease, heart failure, and sepsis." (PMID 26158725, 2015). "The maximal presepsin value was 348 pg/ml (the measured GFR and C-reactive protein level of patients were 21.8 ml/min/1.73m2 and 0.06 mg/dl, respectively), and this values is under the cutoff value for diagnosing sepsis, which was reported to be approximately 400–600 pg/ml." (PMID 26030716, 2015). "Moreover, a recent meta-analysis suggested that procalcitonin was characterized by higher accuracy than the CRP for the diagnosis of late-onset sepsis." (PMID 25685774, 2015). "While further research is needed to confirm our findings, we propose that CRP may be as effective as PCT in predicting the outcome of critically ill patients with severe sepsis and septic shock." (PMID 26367532, 2015). "Some authors suggested a more rapid increase after the beginning of sepsis compared to CRP, and this could allow a more precocious identification of septic neonates." (PMID 25685774, 2015). "In patients with sepsis, levels of urinary and serum NGAL and the prevalence and severity of AKI are strongly associated with severity of illness and inflammation as expressed by APACHE II and CRP." (PMID 25868473, 2015). "Furthermore, approximately 30 % of those with normal CRP were treated with inadequate initial antibiotics, and 13 % progressed to septic shock and 4.9 % had sepsis-attributable mortality." (PMID 26259626, 2015). "Traditional individual markers of sepsis, such as the total white cell count, neutrophil count, and C-reactive protein, lack the specificity to allow them to discriminate between those patients with an inflammatory response to trauma or surgery, for example, and those with a new infection." (PMID 25927426, 2015). "In the meantime, good clinical observation, basic laboratory testing (including complete blood count, platelet levels and CRP), well-conceived "sepsis bundles" including antibiotic guidelines and resuscitation protocols, and sentinel microbiology facilities must continue." (PMID 25710684, 2015). "Biomarkers such as IL-6 and CRP etc. are widely studied in the diagnosis and treatment of sepsis." (PMID 26599367, 2015). "CRP was of only moderate value in predicting sepsis (sensitivity 0.92, specificity 0.36)." (PMID 26305781, 2015). "Recently, a study performed in critically-ill patients suggested that IPF could be a more accurate sepsis biomarker than C-reactive protein (CRP) and procalcitonin." (PMID 25620275, 2015). "However, other studies reported a limited role for CRP to diagnose sepsis or predict outcomes in other clinical scenarios." (PMID 26502877, 2015). "IL-6, and CRP, etc. serve as biomarkers, which may aid clinical decision-making and predicting sepsis-related outcomes." (PMID 26599367, 2015). "Previous studies have shown daily CRP measurements are useful for monitoring the course of sepsis in critically ill patients, and may be used to indicate successful treatment." (PMID 26367532, 2015). "In the clinical sepsis group only 30% and 10% of patients had elevated CRP and IL-6, respectively." (PMID 25894336, 2015). "Thus, initial CRP and albumin levels were combined to ascertain their value as an independent predictor of 180-day mortality in patients with severe sepsis and septic shock." (PMID 26158725, 2015).
Sepsis (continued). "The 16S rRNA assay demonstrated superior performance than blood culture and CRP and may provide a faster, more accurate diagnosis of sepsis in this population of infants." (PMID 26305781, 2015). "In this study, validity of CRP in the diagnosis of sepsis was studied on 147 neonates." (PMID 26150837, 2015). "Of 986 episodes of neonatal BSI, 247 (25.1 %) had CRP ≤10 mg/L at the onset of clinical sepsis." (PMID 26259626, 2015). "This study aimed to examine the part of CRP in neonatal sepsis to see if it can be used as a tool to find the time period when antibiotics treatment can be safely discontinued in case of suspected neonatal septicaemia." (PMID 26150837, 2015). "In this review, we will focus on CRP as it relates to sepsis." (PMID 24772418, 2014). "CRP is a widely used biomarker to discriminate the inflammatory response to sepsis." (PMID 24672147, 2014). "Moreover, increased CRP concentrations have been associated with increased mortality in dogs with SIRS and sepsis." (PMID 25430894, 2014). "CRP was then decreasing, but at D9 a new increase was triggered by sepsis (phase 2)." (PMID 25309760, 2014). "Therefore this study aimed at evaluating the use of serial qualitative CRP assay as a rapid test to accurately predict neonatal septicaemia so as to avoid unnecessary use of antibiotics and to guide the duration of antibiotic therapy." (PMID 25280754, 2014). "The role of CRP in sepsis prognostic value seemed different." (PMID 24672147, 2014). "While the precise diagnostic accuracy of PCT continues to be debated, compared to other biomarkers used in the diagnosis of sepsis including white blood cell counts, absolute neutrophil counts, and C-reactive protein (CRP), PCT is routinely reported as both more sensitive and specific." (PMID 27355024, 2014). "CRP is mostly used to assess the presence of infection and sepsis." (PMID 24475269, 2014). "However, CRP cannot been used as a biomarkerfor prognosis evaluation of patients with sepsis on their first day of admission, and PCT has low sensitivity and specificity for predicting themortality of sepsis." (PMID 24303815, 2014). "In the present study, 58 cases of severe sepsis (including septic shock) were analyzed for the detection of RAS activity-associated, myocardial damage (TNT), pro-BNP, response tissue perfusion (lactate) and inflammatory (CRP) variables." (PMID 24940436, 2014). "There have been several investigations of CRP in sepsis in India." (PMID 24772418, 2014). "Biomarkers such as C-reactive protein (CRP), leukocyte count, lactate and Procalcitonin (PCT) are often used to differentiate between systemic inflammatory response syndrome (SIRS), sepsis, severe sepsis and septic shock as well as for patient risk stratification." (PMID 24533868, 2014). "PCT is considered to have a higher capacity to diagnose sepsis than CRP." (PMID 24903083, 2014). "The aim of the present study was to determine SAA, CRP and albumin concentrations in dogs with sepsis and pyometra and to evaluate whether these inflammatory markers are associated with length of postoperative hospitalization." (PMID 25430894, 2014). "It was previously shown that in comparison with other, frequently used in clinical practice, biomarkers of sepsis including CRP and procalcitonin, suPAR was not a better diagnostic marker." (PMID 24882949, 2014). "Additionally, CRP concentrations can be used as surrogates for the clinical response to antibiotics and the reduction in bacterial load is sepsis." (PMID 23874739, 2013). "Results from the current study showed that F.n. infected galectin-3−/− animals exhibited a reduction in the levels of sepsis mediators such as vascular injury markers thrombopoietin, fibrinogen, as well as acute phase protein CRP and inflammatory cytokines such as TNF-α, IL-6 and IL-1." (PMID 23527230, 2013). "The levels of CRP in sepsis have been shown to be related to mortality and organ failure." (PMID 24167754, 2013).
Sepsis (continued). "In other words, could a cirrhotic patient with Child-Pugh C cirrhosis increase CRP concentrations in the same way as a Child Pugh A cirrhotic patient for the same level of sepsis severity?" (PMID 24286072, 2013). "In earlier studies, the utility of PTX3 as a sepsis marker has been compared with CRP." (PMID 23341967, 2013). "Furthermore, the SAA test has showed better accuracy than the CRP test for the diagnosis of neonatal sepsis in the first suspicion of sepsis." (PMID 23984377, 2013). "In sepsis, for example, elevated CRP correlates with disease severity." (PMID 23866258, 2013). "Using a clinical pathway for neonatal sepsis, which is based primarily on CRP determinations, may minimize antibiotic exposure and shorten hospital stays in asymptomatic infants." (PMID 24244325, 2013). "The usefulness of CRP in sepsis diagnosis has been questioned." (PMID 23883345, 2013). "Comparison of the time course of CRP values in relation to etiologies of sepsis (e.g., peritonitis versus pneumonia) may also be interesting." (PMID 24286072, 2013). "Therefore, CRP was one of the infection markers chosen for this study protocol, as it is easily available and familiar as a reference marker for sepsis." (PMID 23634180, 2013). "Because infection is one of the strongest stimuli of the inflammatory response, we hypothesized that CRP levels at ICU discharge would be an important marker of long-term mortality in patients with sepsis." (PMID 23555017, 2013). "Since inflammatory markers with early kinetics such as IL-8 or IL-6 are not yet routinely available at our institution, we have now adopted a protocol that measures initial CRP values during rule-out of early onset sepsis during routine laboratory tests at 12 hours of age." (PMID 24244325, 2013). "In summary, it may be concluded from the study that sTREM-1 is more ideal than PCT and CRP for early sepsis diagnosis and severity assessment and constitutes an independent risk diagnostic parameter." (PMID 23935252, 2013). "Thus, a single CRP measurement is reasonably useful in the diagnosis of sepsis, which suggests that infection should always be suspected if there is a steady increase in CRP levels over a period of two to three days, and in the absence of any intervention." (PMID 23634180, 2013). "Recently it was reported that CRP strikingly downregulates the C5aR on PMN in patients with sepsis." (PMID 24167754, 2013). "However, CRP concentrations in relation to the severity of sepsis (SOFA, vasopressor dosage, PaO2/FiO2, renal replacement therapy) for each level of cirrhosis were not reported." (PMID 24286072, 2013). "In sepsis CRP was shown to participate in complement activation." (PMID 24167754, 2013). "Heparin Binding Protein (HBP) is an inflammatory mediator contained within neutrophil secretory and azurophilic granules which demonstrated superior sensitivity and specificity to PCT and CRP in identifying patients with severe sepsis in the emergency department." (PMID 23531337, 2013). "The purpose of this study was to evaluate the compliance, effectiveness and safety of implementing CRP-based guidelines in determining empirical antibiotic use in suspected early-onset sepsis in preterm VLBW infants and to measure the association between WBC indices and CRP values over time." (PMID 24244325, 2013). "False negative CRP results in proven clinically significant sepsis have occurred in association with neutropenia." (PMID 24244325, 2013). "Previous research, mainly from Europe, showed that changes over time in biomarkers including PCT and C-reactive protein (CRP) may be used to monitor patients with sepsis, respiratory infections or both in the ICU." (PMID 23787145, 2013). "Pro-calcitonin has also been highlighted as an indicator of inflammation due to infection and there are studies indicating the serum levels of pro-calcitonin may be a better indicator of sepsis severity than CRP." (PMID 23171626, 2012).
Sepsis (continued). "• Regression of sepsis, normalisation of CRP and visual confirmation of complete source control may help to select patients for definitive abdominal closure after NPT even in cases when abdominal bacterial cultures are positive." (PMID 23281649, 2012). "Although the majority of hospitals can widely implement CRP analysis in sepsis diagnosis and prognosis, whether CRP is a good biomarker for early diagnosis of sepsis or bacteremia is still controversial." (PMID 22809118, 2012). "Numerous studies have attempted to identify biomarkers to predict sepsis mortality, including serum C-reactive protein (CRP), Procalcitonin (PCT) levels, and Acute Physiology and Chronic Health Evaluation II scores (APACHE II) and Sequential Organ Failure Assessment scores (SOFA)." (PMID 22719975, 2012). "Regression of sepsis, normalisation of CRP and visual confirmation of complete source control may help to select patients for definitive abdominal closure following NPT even in cases when abdominal bacterial cultures remain positive." (PMID 23281649, 2012). "The AUROC for prediction of sepsis was 0.62, compared to 0.86 for CRP and 0.78 for PCT." (PMID 22221662, 2012). "It has been noted that using pro-calcitonin in sepsis management could increase the validity of the clinical decision since it yields results rapidly and it has a shorter half-life than CRP (by 19 hours)." (PMID 23171626, 2012). "Instead of initial CRP values, CRP values measured a few days after admission may be more helpful for physicians to make judgments on treatment response and sepsis outcome in the ICU." (PMID 23171626, 2012). "Serum sTREM-1, PCT, and CRP levels each have a role in the early diagnosis of sepsis." (PMID 22809118, 2012). "In patients with sepsis, plasma CRP levels were very high (>200 mg/L)." (PMID 22611487, 2012). "CRP concentration in 35% of proved sepsis group was higher than the cut-off value." (PMID 23493845, 2012). "sTREM-1, PCT, and CRP levels are of substantial value for the early diagnosis of sepsis." (PMID 22809118, 2012). "Particularly as CRP was only tested to predict positive blood culture which may represent only a proportion of neonates with sepsis, especially if the patient had been on antibiotic therapy before presentation as is common in Sub-Saharan Africa." (PMID 22958461, 2012). "Instead of looking at high CRP levels on the day of ICU admission due to sepsis, a CRP level > 100 mg/L on the third day of ICU may be as good a predictor of mortality as a high SOFA score." (PMID 23171626, 2012). "We believe that the 3rd day CRP value can be used in clinical practice in the ICU to reveal mortality risk and is comparable with the SOFA score when its level is high on third day after initiation of treatment for sepsis (> 100 mg/L)." (PMID 23171626, 2012). "Therefore a protein-microarray for point-of-care testing that simultaneously quantifies the sepsis associated serum proteins IL-6, IL-8, IL-10, TNF alpha, S-100, PCT, E-Selectin, CRP and Neopterin has been developed." (PMID 22438722, 2012). "IL-6 and CRP values were significantly higher during the sepsis attacks." (PMID 22672862, 2012). "However, CRP levels on the day of sepsis diagnosis have proved to have poor predictive value for mortality." (PMID 22719975, 2012). "Recently, ∆ CRP was shown to be a predictor of mortality from sepsis in dogs." (PMID 23171626, 2012). "Human clinical studies have shown that in septic patients there are significant decreases in plasma PON1 (paraoxonase and arylesterase) activity, and this is negatively correlated with C-reactive protein (CRP), which is produced in response to the oxidizing environment induced by sepsis." (PMID 22824324, 2012). "However, because the concentration of CRP increases rather slowly in the initial phase of inflammatory response to pathogens, the sensitivity of CRP testing at the time of sepsis evaluation is insufficient." (PMID 21765851, 2011).
Sepsis (continued). "Likewise, a significant, but less strong correlation (r = .54, p = .002) between LBP and CRP was described in patients with sepsis and septic shock." (PMID 21901123, 2011). "At this cut-off value, all infants with fungi-related sepsis (n = 6) had SC levels above normal value, whereas only 2/6 had deranged values of traditional markers (1 with platelet count >500.0 × 103/mm3; 1 with CRP >10 mg/dL)." (PMID 21765851, 2011). "Maximum C-reactive protein during sepsis was at median 44 mg/l (range 22 - 261)." (PMID 21595972, 2011). "Overall, these results suggest that dynamic changes of sTREM-1 may better reflect the body's state of inflammatory response and sepsis severity simultaneously making sTREM-1 superior to CRP and PCT." (PMID 21356122, 2011). "There is debate within the literature whether procalcitonin is a specific marker of infection, though receiver operating curve (ROC) characteristics in some studies suggest that the performance of procalcitonin as a marker of sepsis is superior to that of CRP." (PMID 21366899, 2011). "Serial CRP values taken 24–48 h after the onset of symptoms have an improved sensitivity and specificity when compared with single CRP values at presentation for diagnosis of sepsis." (PMID 22164179, 2011). "The differences in urine sTREM-1, WBC counts and serum PCT levels at these six different time points were statistically significant, with the severe sepsis group having all-time higher values, and also showing a higher CRP level on days 5, 7, and 10, which were also statistically significant." (PMID 22023777, 2011). "A DNI value > 6.5% was a better indicator of severe sepsis/septic shock than C-reactive protein, lactate, white blood cell count, and absolute neutrophil count (sensitivity, 81.3%; specificity, 91.0%; positive predictive value, 88.6%; and negative predictive value, 84.7%)." (PMID 22040292, 2011). "We examined the utility of serum levels of soluble triggering receptor expressed on myeloid cells-1 (sTREM-1) for the diagnoses, severity assessments, and predicting the prognoses of patients with sepsis and compared sTREM-1 values with those of C-reactive protein (CRP) and procalcitonin (PCT)." (PMID 21356122, 2011). "Positive microbiological cultures or clinical and laboratory criteria very suggestive of sepsis (e.g., temperature instability, poor feeding, apnea, irregular respiration, positive C-reactive protein [CRP] and micro-erthrocyte sedimentation rate [micro-ESR]) and died in first 28 days of life." (PMID 21501428, 2011). "Alleles -7202G and 248Ser, and the 248Ser-602Ile haplotype were associated with circulatory dysfunction among severe septic patients (0.001≤p≤0.022), and with reduced IL-10 (0.012≤p≤0.047) and elevated CRP (0.011≤p≤0.036) serum levels during the first week of sepsis development." (PMID 21048935, 2010). "The aim of the present study was to investigate the value of thromboelastometry variables as potential biomarkers of sepsis in critically ill adults and to compare these hemostasis-related biomarkers with the established markers procalcitonin, interleukin 6, and C-reactive protein." (PMID 20929576, 2010). "LBP, IL-6 and CRP levels may serve as good biomarkers for identifying children with severe sepsis and bacteraemia and, thus, may be routinely used in clinical practice." (PMID 20158885, 2010). "Delayed elevation of CRP started on the fourth day of ICU admission in patients with sepsis." (PMID 20230641, 2010). "A year 2005 review concludes that the ability of CRP level to reflect the severity of sepsis may be limited." (PMID 20500875, 2010). "Complete blood count, CRP and cultures on recovery phase of sepsis." (PMID 20653967, 2010). "Complete blood count, CRP and cultures on acute phase of sepsis." (PMID 20653967, 2010). "Furthermore, LBP, IL-6 and CRP were significantly higher in children with severe sepsis compared to those ones with less severe sepsis (p < 0.001)." (PMID 20158885, 2010).